PLXNB1 (plexin B1)
Diseases named in the same sentence as PLXNB1 in open-access papers (continued):
Sharing a sentence is not in itself a finding about the gene and the disease.
tumor (continued). "They showed that the tumor cell-derived Sema4A engagement of Plexin B1 on CD8+ T cells increased the effector function of CD8+ T cells and improved the anti-tumor efficacy of PD-1 blocking Ab." (PMID 38259471, 2023). "SEMA4D binds three types of receptors, Plexin-B1 (PLXNB1), Plexin-B2 (PLXNB2), and CD72, which are all expressed by APCs, endothelial cells, and tumor cells." (PMID 34948104, 2021). "SEMA4D (CD100) binds 3 types of receptors, Plexin-B1 (PLXNB1), Plexin-B2 (PLXNB2), and CD72, which are all expressed by APCs (B cells, monocytes, DCs), endothelial cells, and tumor cells." (PMID 33741032, 2021). "We generated a recombinant Plexin B1 sema domain‐Fc fusion protein called B1SP that effectively inhibited SEMA3C‐induced RTK signaling and tumor progression in vivo." (PMID 29348142, 2018). "In ErbB-2-overexpressing tumour cells, such as BT-474 and MT-2, RhoA activity was strongly reduced by blockade of the IKK-complex or knockdown of Plexin-B1." (PMID 25137062, 2014). "Consistent with a central role of Plexin-B1 in ErbB-2-induced tumour progression, blockade of IKK also reduced tumour cell invasiveness." (PMID 25137062, 2014). "PLXNB1, acting as the high‐affinity receptor for SEMA4D, might exert a more intricate function within the tumour microenvironment." (PMID 39443302, 2024). "In addition, Semaphorin 4D (Sema4D) and its receptor, Plexin-B1, were found to cooperate with VEGF to promote angiogenesis and tumor progression through attracting Plexin-B1-expressing endothelial cells into the tumor to enhance growth and vascularity." (PMID 37986114, 2023). "The production of SEMA4D by TAMs in the tumor stroma has been shown to sustain tumor angiogenesis and vessel maturation; while SEMA4D expressed by cancer cells sustains angiogenesis by binding plexin-B1 expressed by endothelial cells." (PMID 35440004, 2022). "Stable silencing of Plexin-B1 impaired Sema4D-mediated activation of the RhoA and SRPK1 signaling in tumor cells, and resulted in a reduction of microvessel density in xenografts generated in vivo, due to an unknown mechanism." (PMID 31052281, 2019). "Constitutive activation of Met in tumor cells with high Plexin-B1 can occur in the absence of Sema4D." (PMID 29971044, 2018). "Developmental biology is added to IGC samples because of the semaphorins interactions (genes PLXNB1 and RHOA), which have been found to function as tumor suppressors and inhibit tumor progression by various mechanisms; however, they also can function as inducers and promoters of tumor progression." (PMID 40028213, 2025). "Sema4D produced by tumor cells may also act as an autocrine or paracrine signal to suppress migration; nonpolarized activation of Plexin-B1 over the whole cell results in cell collapse in vitro." (PMID 36936664, 2023). "We do not postulate a role for Sema4D/Plexin-B1 signaling in the ability of certain tumor cell types to home to bone, but once at the site the end result of such alteration in osteoblast-osteoclast communication would be a more favorable microenvironment in which to establish a metastatic niche." (PMID 26910109, 2016). "Moreover, we found that the expressions of Ezh2 and plexin-B1 were not negatively correlated with miR-214 in miR-214-downregulated HCC tumor samples (data not shown)." (PMID 22359598, 2012).
cancer (35 papers, 2007 to 2025). A tumor composed of atypical neoplastic, often pleomorphic cells that invade other tissues. "The PLXNB subgroup were associated with both survival advantage and disadvantage of a number of cancer types, but PLXNB1 and PLXNB2 were more associated with better survival, while PLXNB3 was more associated with worse survival." (PMID 32640719, 2020). "Sema4D and Plexin-B1 are abnormally expressed in various cancers and have been associated with invasive phenotypes and poor prognosis." (PMID 29971044, 2018). "Plexin-B family members contribute to cancer progression, for example Sema4D induces invasive growth of cancer cells by signalling through Plexin-B1, which associates with and activates the tyrosine kinase receptors Met or Ron." (PMID 29040270, 2017). "With respect to c-Met, plexin B1 and its ligand, semaphorin 4D, have been most studied, and both have been implicated in cancer progression." (PMID 28536399, 2015). "Loss of plexin-B1/plexin-B2 could represent a mechanistic basis for the loss of contact inhibition, a hallmark of cancer." (PMID 37627074, 2023). "Taken together, these data strongly suggest that loss of Plexin-B1/Plexin-B2 could represent a mechanistic basis for the loss of contact inhibition, a hallmark of cancer that has remained poorly understood on a molecular level." (PMID 33637728, 2021). "Plexin-B1 has been implicated in the processes of cell mobility and cancer metastasis." (PMID 21059203, 2010). "Angiogenesis can promote the growth of cancer cells, while both NRP2 and PLXNB1 have been verified to be vascular-associated genes." (PMID 36460803, 2023). "The strongly reduced expression levels of Plexin-B1 and Plexin-B2 correlated with an impaired ability of the primary human cancer cells to exclude YAP from the nucleus at high cell densities." (PMID 33637728, 2021). "Intriguingly, we found that mechanosensation through Plexin-B1/Plexin-B2 regains biological relevance in the adult murine epidermis for the suppression of cancer cell proliferation." (PMID 33637728, 2021). "While blocking the Sema4D/Plexin-B1 complex is of potential benefit in cancers and neuroinflammatory diseases, some cancers are growth inhibited by Sema4D signaling." (PMID 29971044, 2018). "To analyze the functional relevance of the observed role of the IKK-complex in signalling through B-family plexins, we studied Plexin-B1-mediated signalling in ErbB-2-expressing cancer cells." (PMID 25137062, 2014). "Recently clinical studies have also provided further insights into the significance of Plexin-B1 in human cancers." (PMID 20858260, 2010). "Plexin-B1 is overexpressed in some cancers and appears to act as a tumor suppressor gene in others." (PMID 36936664, 2023). "Cancer cell lines that express higher levels of Plexin-B1 exhibit increased perineural invasion." (PMID 29971044, 2018). "In cancer cells that express both Sema4D and Plexin-B1, the pair could function in an autocrine/paracrine manner, although this requires future study." (PMID 29971044, 2018). "While not directly linked to malignant transformation, Sema4D/Plexin-B1 signaling contributes to many critical aspects of cancer progression, including proliferation, invasion, angiogenesis, immune escape, and metastasis." (PMID 29971044, 2018). "The differential function of Sema4D/plexin in tumour biology is also illustrated by the variable results in studies examining the expression levels of these molecules in the disease progression of human cancers with both low Sem4D and high plexin-B1, leading to poorer survival." (PMID 28536399, 2015). "Since Sema4D is expressed in T-cells and certain types of cancer cells, Plexin-B1-mediated and IKK-complex-dependent RhoA activation might contribute to reduced bone formation under these circumstances." (PMID 25137062, 2014). "The invasive activity of cancer cells overexpressing ErbB-2 is mediated by Plexin-B1 and RhoA." (PMID 25137062, 2014).
cancer (continued). "Rho GTPases play important roles in regulating the actin cytoskeleton during developmental processes such as cell adhesion, cell migration, axon guidance, cell cycle events and membrane transport, suggesting potential involvement of Plexin-B1 in cancer progression and metastasis." (PMID 21059203, 2010). "Met was activated in the presence of Plexin-B1 expression in a majority of these cancers." (PMID 20858260, 2010). "Additionally, plexin B1 plays a role in modulating immune responses, which may influence cancer development." (PMID 39408230, 2024). "Therefore, the PLXNB1/SEMA4D axis may be a relevant cancer biomarker that warrants further investigation, with SEMA4D's specific role in CRC remaining unclear." (PMID 39443302, 2024). "Activated plexin B1 might transactivate MET to modulate cancer growth and migration." (PMID 32296018, 2020). "Furthermore, we show that Plexin B1 is a key SEMA3C receptor in cancer cells." (PMID 29348142, 2018). "Our previous findings indicate that SEMA3C functions as a secreted soluble autocrine growth factor that drives cancer growth by transactivating multiple RTKs such as EGFR, HER2 and MET via Plexin B1." (PMID 37443749, 2023). "In castration-resistant prostate cancer, plexin-B1 was observed to transduce the signals of sema3C together with NRP-1/2 and promote cancer growth by activation of EGFR, ErbB2, and MET." (PMID 37627074, 2023). "The expression levels of PLXNB1, PTK2, and IFI30 in the cancer group were lower than those in the normal group." (PMID 36211454, 2022). "Among them, SEMA3F, SEMA4C, PLXNB1 and PLXNB2, involved in cancer progression and in immune system suppression, were highly expressed." (PMID 26784191, 2016). "Although not shown in most studies involving cancer cell lines, another line of investigation of Sema4D and Plexin-B1 interactions centered on the collapse of neurite outgrowth." (PMID 20858260, 2010). "Elevated Plexin-B1 expression has been found in diverse human cancers and in non-neoplastic tissues, and it mediates diverse biological and pathological activities." (PMID 21059203, 2010). "These different and even opposing results reflect the fact that the exact biological function of Plexin-B1 in tumorigenesis and cancer progression is not yet clear." (PMID 21059203, 2010). "The majority of the tested cancer types showed positive correlation between the expression of NRP1, NRP2, PLXNC1 and PLXND1, negative correlation between expression of PLXNB1, and the three scores." (PMID 32640719, 2020).
neurodevelopmental disorder (1 paper, 2021). A behavioral and cognitive disorder with onset during the developmental period that involves impaired or aberrant development of intellectual, motor, or social functions. "Further analysis on CNV shows enrichment of de novo CNVs for both PLXNB1 and KANK1 gene within ASD and neurodevelopmental disorder cases." (PMID 34802461, 2021).
PLXNB1 also shares sentences with these, for which no sentence is quoted: pancreatic cancer (4 papers); prostate tumor (4); infection (3); acute myeloid leukemia (2); colon cancers (2); diabetic retinopathy (2); migraine (2); soft tissue sarcoma (2); allergic rhinitis (1); atherosclerosis (1); autism (1); brain tumors (1); chronic hepatitis C virus infection (1); cutaneous squamous cell carcinoma (1); esophageal squamous cell carcinoma (1); gastric cancer (1); Hepatic fibrosis (1); Huntington disease (1); neurological disorders (1); non-small cell lung carcinoma (1); oral cancer (1); oral lichen planus (1); osteoarthritis (1); ovarian cystadenocarcinoma (1); ovarian serous carcinoma (1); pancreatic ductal adenocarcinoma (1); renal carcinoma (1); Rett syndrome (1); schizophrenia (1); serous borderline ovarian tumors (1).
A further 5 diseases each share a sentence with PLXNB1 in 1 paper.